STAT1 (signal transducer and activator of transcription 1)
Diseases named in the same sentence as STAT1 in open-access papers (continued):
Sharing a sentence is not in itself a finding about the gene and the disease.
ovarian cancer (71 papers, 2005 to 2025). A primary or metastatic malignant neoplasm involving the ovary. "The upregulation of STAT1 is associated with docetaxel resistance in prostate cancer cells 40 and cisplatin resistance in ovarian cancer cells." (PMID 34522170, 2021). "An in vitro study with one endometrial cancer and two ovarian cancer cell lines harboring JAK1 frameshift mutations demonstrated that JAK1 mutations impede STAT1 posphorylation and upregulation of antigen presenting machinery components LMP2 and TAP1." (PMID 27213585, 2016). "In cancer, STAT3 has been implicated in EGF-mediated EMT in ovarian cancer cell lines and STAT1 has been reported to inhibit angiogenesis in murine fibrosarcoma tumor cells." (PMID 24274066, 2013). "Moreover, high expression levels of STAT1 were also revealed to be linked to a better prognosis in patients with ovarian cancer." (PMID 36968603, 2023). "In general, class I HDAC1-3 are upregulated during ovarian cancer progression and correlate with a poor patient survival; while class II HDAC4 overexpression is linked with platinum resistance as well deacetylation of STAT1 in primary ovarian cancer cells isolated from ovarian cancer patients." (PMID 31426393, 2019). "In addition, 14 ovarian cancer lines were observed for resistance to platinum compounds where STAT1 was associated with resistance to cisplatin and AMD473." (PMID 24460726, 2014). "Ovarian cancer cells treated with HDACi can promote the acetylation of STAT1 and reduce the drug resistance." (PMID 37935080, 2024). "Further research confirmed that GBP5 in ovarian cancer cell can induce canonical pyroptosis through JAK2/STAT1 pathway, thereby restraining the progression of ovarian cancer." (PMID 38817865, 2024). "Overall, the IL-27-induced gene expression pattern and the employed STAT1/IRF/CIITA signalling pathways identified here in IEC resemble that described for IFN-γ in different cell types such as hepatocytes or ovarian cancer cells." (PMID 37818353, 2023). "The JAK-STAT signaling pathway, especially transcription factor STAT1, was verified to be positively correlated with GCH1-high expression, highlighting the underlying role of STAT1 in the regulation of GCH1 in breast and ovarian cancers." (PMID 36793373, 2023). "We identified a series of necroptosis‐related genes involved in the pathogenesis of ovarian cancer, including STAT1, CASP8, and IFNB1, and provided a preliminary analysis of their interactions." (PMID 37681751, 2023). "Differentially, in high-grade (G3, G4) ovarian cancer, STAT1, 2, 4, and 5A were highly expressed, while STAT3 and STAT5B were mostly lowly expressed." (PMID 36524006, 2022). "According to research, ovarian cancer tissues exhibited higher STAT1 but lowered STAT2-6 expression than normal tissues." (PMID 36524006, 2022). "Previous studies revealed that STAT1 is overexpressed in malignant tumors and plays an oncogenic role in patients with cancer, such as breast and ovarian cancers." (PMID 34572789, 2021). "In contrast, another study has shown that the activation of the STAT1 pathway and downstream interferon-stimulated genes contributes to platinum drug resistance in human ovarian cancer cells." (PMID 33578797, 2021). "Summary of molecules that regulate STAT1 with biological function and chemo-responsiveness in ovarian cancer cells." (PMID 33834023, 2021). "Over-expressed histone deacetylase 4 (HDAC4) interacted with STAT1, decreasing the levels of STAT1 acetylation and promoting STAT1 nuclear localization, thereby leading to cisplatin resistance in ovarian cancers." (PMID 34522170, 2021). "The low expression of ANP32E, STAT1, GPRC5A, EGFL6, and PMP22 was positively associated with overall survival time of ovarian cancer." (PMID 34660776, 2021). "Combining TCGA ovarian cancer dataset, we identified differentially expressed marker genes that were significantly associated with prognosis of ovarian cancer, including ANP32E, STAT1, GPRC5A, EGFL6, PMP22, FBXO21, and CYB5R3." (PMID 34660776, 2021).
ovarian cancer (continued). "The overexpression of STAT1 prevented the suppressor role of TGFβ on cell proliferation, migration, and invasion in epithelial ovarian cancer cells." (PMID 33498521, 2021). "The activation of STAT1 is triggered by JAK ligands and increased expression levels of STAT1 have been reported in patients with ovarian cancer." (PMID 33177242, 2020). "Overexpression or knockdown of STAT1 can directly induce or suppress ovarian cancer cell proliferation, migration, and invasion." (PMID 33177242, 2020). "Studies of breast and ovarian cancer found that STAT1 is overexpressed in malignant tumors and plays an oncogenic role." (PMID 32793281, 2020). "We identified that the transcription and expression of STAT1 is increased in STAT3 KO ovarian cancer cells." (PMID 31534498, 2019). "Using specific primers recognizing to STAT1 isoforms, we found that the mRNA of STAT1α and total STAT1 was significantly increased in ovarian malignant tumors." (PMID 29751820, 2018). "Activating the FAK/STAT1 signaling pathway induces a malignant potential in ovarian epithelium and targeting this signaling pathway is a good therapeutic strategy for ovarian cancer." (PMID 29751820, 2018). "Our results showed that high expression of STAT1 mRNA was correlated to a better OS for all the ovarian cancer patients, particularly for serous cancer patients." (PMID 28536310, 2017). "IFN-γ induced up-regulation of p21 and activation of STAT1 protein in epithelial cell carcinoma and ovarian cancer cell lines." (PMID 26993600, 2016). "For instance, HDAC4 positively regulates STAT1 activation and mediates STAT1-dependent platinum resistance in ovarian cancer." (PMID 26654227, 2015). "HDAC4 deacetylates STAT1, thereby enhancing phosphorylation and nuclear translocation of STAT1 upon cisplatin-treatment in platinum resistant ovarian cancer cells (exposure to chemotherapy)." (PMID 26654227, 2015). "Particularly, STAT1 negatively regulates the cell cycle by inducing p21 WAF1/CIP1 in ovarian cancer." (PMID 22863767, 2012). "The acetylation of STAT1 also determined the sensitivity of ovarian cancer cells to cisplatin." (PMID 37935080, 2024). "Interestingly, the high expression of STAT1 led to satisfying OS of ovarian cancer, rectum adenocarcinoma, and sarcoma, whereas in several cancers including pancreatic cancer, and lung adenocarcinoma, the high expression of STAT1 was correlated with poor OS." (PMID 39208654, 2024). "The tumor suppressor gene RFPL1S may slow ovarian cancer progression by inhibiting IFN-β/STAT1 signaling." (PMID 38792557, 2024). "The contradictory role of STAT1 in promoting and inhibiting cancer also existed in invasion and metastasis, angiogenesis, immunologic responsiveness, and chemotherapeutic drug reactivity of ovarian cancer." (PMID 36524006, 2022). "STAT1 was also found to mediate an important anti-tumor response for squamous cell carcinoma of the head and neck, with increased STAT1 expression inhibiting the progression of ovarian cancer and improving the prognosis of both of these cancers." (PMID 35692770, 2022). "Additionally, the overexpression of STAT1 in both malignant breast and ovarian cancer is likely to induce tumor proliferation and other oncogenic activity." (PMID 35158821, 2022). "Target genes regulated by STAT1 with biological function in ovarian cancer cells." (PMID 33834023, 2021). "The silencing of lncRNA-NRCP could reduce the levels of glucose-6-phosphate isomerase ALDOA and ALDOC. lncRNA-NRCP via STAT1 could promote glycolysis in ovarian cancer cells." (PMID 33123468, 2020).
ovarian cancer (continued). "STAT1 has been recently identified as a drug resistance biomarker in ovarian cancer." (PMID 29751820, 2018). "The overexpression of STAT1 in ovarian cancer may result in the tumorigenic effect of TGF-β signaling and therefore partially explains the controversial behavior of TGF-β in tumorigenesis." (PMID 29751820, 2018). "But so far, studies about STAT1 in ovarian cancer are limited." (PMID 28536310, 2017). "Our results show that high mRNA expression of STAT1, STAT4, STAT5a, STAT5b, and STAT6, are correlated to a better OS of ovarian cancer patients, especially the high level of STAT1 and STAT4 are significantly related to a favorable OS for serous ovarian cancer patients." (PMID 28536310, 2017). "High mRNA expression of STAT1 was related to a better OS in all the ovarian cancer patients, HR =0.84 (0.71−0.98), P=0.025, especially for serous ovarian cancer patients, HR =0.81 (0.68−0.95), P=0.0093, but not in endometrioid cancer patients, HR =300485201.86 (0−Inf), P=0.17." (PMID 28536310, 2017). "In summary, our results show that high mRNA expression of all the individual STATs except STAT2 and STAT3 are correlated to a better OS for all the ovarian cancer patients, especially the high level of STAT1 and STAT4 are significantly related to a favorable OS for serous ovarian cancer patients." (PMID 28536310, 2017). "Comparison of cell line signatures revealed that the opposing directions of mRNA transcript intensity scores (z-scores) for Sep15 and Stat-1 were particularly significant (r = −0.65, P<0.01) for human cancer cell lines derived from central nervous system, leukemia and ovarian cancers." (PMID 25886253, 2015). "Therefore, we speculated that CRL4 might also regulate STAT1 expression in cisplatin-resistant ovarian cancer cells." (PMID 30718461, 2019). "Suppression of STAT1 may be a potential therapeutic strategy for targeting ovarian cancer." (PMID 29751820, 2018). "Immunohistochemistry for JAK1, STAT1, and STAT3 was performed on samples of patients with ovarian cancer to confirm the correlation between JAK-STAT family expression and platinum treatment response." (PMID 40883550, 2025). "Ovarian cancer patients with a high level of STAT4 and 6 gene expression or a low level of STAT1 gene expression had high OS." (PMID 36524006, 2022). "We found that the expression levels of STAT1, ANP32E, GPRC5A, and EGFL6 were all significantly higher in ovarian cancer tissues compared with normal tissues." (PMID 34660776, 2021). "The signal transducer and activator of transcription 1 (STAT1) is a transducer protein and acts as a transcription factor but its role in ovarian cancer (OC) is not completely understood." (PMID 33834023, 2021). "STAT1, as the first member of STAT family, plays an oncogenic role in patients with breast and ovarian cancers." (PMID 34074347, 2021). "Our recent studies show that STAT1 and TGF-β affect ovarian malignant tumor growth, progression, and metastasis." (PMID 32516753, 2020). "In order to examine the significance of STAT1 interaction with TGF-β receptors, we performed overexpression or knockdown of STAT1α/β in ovarian cancer cells (SK-OV-3) and examined the status of the TGF-β signaling pathway." (PMID 29751820, 2018). "With regard to clinical stages, while STAT5a, STAT5b, and STAT6 were related to a positive OS both in stages I/II and III/IV ovarian cancer patients, STAT1 and STAT4 were correlated to a favorable OS in stages III and IV ovarian cancer patients." (PMID 28536310, 2017).
ovarian cancer (continued). "In ovarian cancer, the lncRNA NRCP interacts with STAT1 and RNA polymerase II, leading to increased expression of glucose-6-phosphate isomerase and modulation of glycolysis." (PMID 29371936, 2017). "In particular, we previously showed that STAT1 and STAT3 signaling was required for expression of IDO and PD-L1 in ovarian cancer cells." (PMID 27683036, 2016). "It is suggested that STAT1, STAT4, and STAT6 may be potential targets for the proper treatment of ovarian cancer." (PMID 36524006, 2022). "Based on our findings, STAT1, STAT4, and STAT6 may be viable therapeutic targets for ovarian cancer." (PMID 36524006, 2022). "Furthermore, marker genes, STAT1, ANP32E, GPRC5A, and EGFL6, were highly expressed in ovarian cancer, while PMP22, FBXO21, and CYB5R3 were lowly expressed in ovarian cancer." (PMID 34660776, 2021). "STAT1, a member of STAT family, has been confirmed to be highly expressed in ovarian cancer." (PMID 34660776, 2021). "First, we compared the endogenous expression of STAT1 between non-tumorous ovarian epithelial cell line HOSEpiC and ovarian cancer cell lines OVCAR-3 and SK-OV-3." (PMID 29751820, 2018). "We found that the expression of STAT1α, STAT1β, and total STAT1 mRNA was higher in ovarian cancer cells (OVCAR-3 and SK-OV-3) than in non-tumorous cells (HOSEpiC)." (PMID 29751820, 2018). "The current study showed that the expression level of STAT1 was higher in ovarian cancer cells (OVCAR-3 and SK-OV-3) than non-cancerous ovarian cells (HOSEpiC)." (PMID 29751820, 2018). "Thus, the suppression of STAT1 was suggested as a potential therapeutic strategy in ovarian cancer treatment, albeit no in vivo experiments were performed in this article." (PMID 33498521, 2021). "STAT1 expression was higher in ovarian cancer cells than noncancerous cells." (PMID 29751820, 2018). "In EGF-STAT1 and EGF-STAT3, both gene pairs are involved in pancreatic cancer, EGF pathway, and signal transduction pathway; both STAT1 and STAT3 are activated by the Jak kinase in response to EGF, where JAK2/STAT3 signaling is required for EGF-driven ovarian cancer." (PMID 23940583, 2013). "High expression of STAT1, STAT3, STAT4, and STAT6 mRNA were correlated to a better OS in grade III ovarian cancer patients, but not in grade I or II ovarian cancer patients." (PMID 28536310, 2017). "Here we found that phosphorylation of STAT1, as well as STAT4 and STAT6 (not shown) were simultaneously activated by PAF treatment in BRCA1-mutant ovarian cancer cells (UWB1)." (PMID 20576130, 2010). "Activated STAT1 phosphorylation was further confirmed in two additional BRCA1-mutant HOSE cell lines, but not shown in wild type HOSE-E6E7 and ovarian cancer (OVCA429) cells." (PMID 20576130, 2010). "We found that the enhanced phosphor-STAT1 was neither observed in the wild type normal ovarian epithelial HOSE-E6E7 cells, nor in the wild type ovarian cancer cells (OVCA429), but only found in BRCA1-mutant cell lines (HOSE-642, HOSE-636, and UWB1)." (PMID 20576130, 2010). "Also, expression of p-STAT3 and p-STAT5 but not p-STAT1 and p-STAT6, were significantly higher in ovarian cancer cells compared to benign and normal tissues." (PMID 34358244, 2021). "Another study found that the blockade of Jaks by AG490 enhanced the sensitivity of cisplatin-resistant ovarian cancer cells to AMD473, but not cisplatin 41, highlighting the importance of an elevated expression of STAT1 in the acquisition of the “off-target effects of alisertib”." (PMID 34522170, 2021).
ovarian cancer (continued). "However, only STAT1 but not STAT3 siRNA knockdown impeded IL-27-induced PD-L1 protein expression, consistent with previous reports examining T cells and ovarian cancers." (PMID 31730010, 2019). "Interestingly, we noted an increase in STING and STAT1 levels only in T80 cells and not in ovarian cancer cells upon dsDNA transfection suggesting that the absence of IRF3 activation could be due to an altered upstream signaling involving STING and STAT1." (PMID 25658875, 2015).